SHANK3 (SH3 and multiple ankyrin repeat domains 3)
Diseases named in the same sentence as SHANK3 in open-access papers (continued):
Sharing a sentence is not in itself a finding about the gene and the disease.
autism (continued). "In this regard, researchers have recently developed a macaque (Macaca fascicularis) model of autism with SHANK3 mutations using the CRISPR–Cas9 (clustered regularly interspaced short palindromic repeats–CRISPR-associated protein 9) gene-editing system." (PMID 32383208, 2020). "We report here that δ-catenin, which is encoded by CTNND2, an autism candidate gene, directly interacts with the Ank domain of Shank3 at postsynaptic sites through its Armadillo-repeat domain." (PMID 33115499, 2020). "An animal-based study of Shank3+/- and Shank-/- transgenic mouse compared with prenatal zinc-deficient autism mouse model, which are offspring from zinc-deficient diet fed mice, showed diverse brain region abnormalities in different models of ASD." (PMID 32244359, 2020). "In this study on autism mouse models, SHANK3-deficient mice were compared to PZD mice in terms of neuroanatomical peculiarities measured by structural MRI." (PMID 30853900, 2019). "The Shank3 mutation is strongly associated with autism and schizophrenia in humans and a guanine insertion at position 1227 in Shank3 caused a frameshift mutation, yielding truncated SHANK333." (PMID 31481684, 2019). "There is strong indication that SHANK3 gene mutations or variations are associated with increased autism risks, SHANK3 point mutations, truncations, and disruption by chromosome translocation have been all reported in ASD cases." (PMID 30918484, 2019). "Phelan–McDermid syndrome (PMS) is a rare genetic disorder in which one copy of the SHANK3 gene is missing or mutated, leading to a global developmental delay, intellectual disability (ID), and autism." (PMID 30302388, 2018). "Here we performed single-molecule fluorescence in-situ hybridization (smFISH) to label mRNA coding for the autism-risk gene SHANK3, and establish a protocol for puncta quantification." (PMID 30064494, 2018). "In several patients with autism, deletions, nonsense, missense and splice site mutations have been found that affect the function of one SHANK3 allele." (PMID 29875651, 2018). "The spine phenotypes of autism-linked proteins have been variable, but, for example, Shank3 overexpression results in an increase in mushroom spines and in spine head width, similar to α-actinin-4." (PMID 30123108, 2018). "Mutations in SHANK1–3 are prevalent in patients with autism spectrum disorders (ASD), and loss of one copy of SHANK3 causes Phelan-McDermid Syndrome, a syndrome in which Autism occurs in >80% of cases." (PMID 30405356, 2018). "The global Δe4−22 mice display abnormal social behaviors, aberrant ultrasonic vocalizations (USVs), and increased repetitive responses that resemble the core behavioral features of the autism associated with SHANK3-related disorders." (PMID 29700290, 2018). "A single duplication was found on gene SHANK3 at 22q13.33 which is associated to mild autism with normal intellectual quotient." (PMID 28174603, 2017). "Deletion of the human SHANK3 gene near the terminus of chromosome 22q13 is associated with Phelan–McDermid syndrome and autism." (PMID 27458336, 2016). "Mechanistically, several actin regulators including Abp1, cortactin, cofilin, and Rac1, have altered expression or activity associated with Shank3 deficiency or autism-related mutations that contribute to dendritic spine reduction and synaptic dystrophy." (PMID 27909399, 2016). "Here, we describe a complete knockout mouse model of the autism-associated Shank3 gene, with a deletion of exons 4–22 (Δe4–22)." (PMID 27161151, 2016). "The haploinsufficiency of Shank3 or the loss of one functional copy of the Shank3 gene results in chromosome 22q13 deletion syndrome or Phelan-McDermid syndrome and autism." (PMID 27047540, 2016).
autism (continued). "Altered function of all three SHANK genes have been implicated in autism, with SHANK3 showing the highest prevalence." (PMID 27909399, 2016). "Given its crucial role in the etiology of PMS and autism, studying the impact of a loss of SHANK3 will allow for a detailed assessment of cellular and molecular mechanisms that underlie pathology." (PMID 26137200, 2015). "A duplication of this region is linked with developmental delay and the region also contains the gene SHANK3, which has been associated with autism." (PMID 26379700, 2015). "In fact, P1 has both an early truncating mutation in SHANK3, as well as a 17q duplication, and has one of the more severe presentations observed at the Seaver Autism Center." (PMID 26045941, 2015). "Using various molecular genetics approaches, we have described an unusually complex transcriptional profile for Shank3, a strong human autism causative gene, in the mouse brain." (PMID 25071925, 2014). "Shank3 overexpression promotes the formation of new synapses and dendritic spines and regulates their shape and size, whereas Shank3 knockdown or autism-associated Shank3 mutations specifically impair glutamate signaling at synapses." (PMID 24652766, 2014). "Individuals with SHANK3 truncating mutations displayed autism with moderate to severe/profound ID (mean IQ: 31±8)." (PMID 25188300, 2014). "PMS is both one of the most penetrant and one of the most common monogenic causes of autism, and recent studies have shown SHANK3 deletion or mutation in up to 1.7% of individuals with ASD." (PMID 24652766, 2014). "Remarkably, IGF-1 treatment restores synaptic deficits in neurons from 22q11.2 deletion syndrome patients, a syndrome characterized by an increased risk of SZ and ASD, as well as in a SHANK3-deficient mouse model of autism." (PMID 25061506, 2014). "SHANK3 mutations identified in autism affect the development and morphology of dendritic spines via an actin-dependent mechanism." (PMID 22509352, 2012). "The over-representation of rare, potentially disruptive variants in genes previously implicated in ASD (TSC1, TSC2, SHANK3) provides validation of this approach to detect genes that contribute genetic risk in autism." (PMID 22558107, 2012). "Mutations in SHANK3 have been reported in individuals with mental retardation, autism, and pervasive developmental delays." (PMID 22509352, 2012). "SHANK3 is a post-synaptic density protein involved in the regulation of synaptic transmission, and has been implicated in both autism and schizophrenia." (PMID 23300510, 2012). "Our identification of increased genetic variation in SHANK3 in autism cases supports the emerging view of SHANK3 as an important autism-risk gene." (PMID 22558107, 2012). "The most convincing genetic etiologies arise from syndromes which display autism as one part of the phenotype, such as the Fragile(X) and Rett, or other single genes with rare mutations in autism, such as those in SHANK3." (PMID 22039484, 2011). "As autism is a heterogeneous disease, the rare mutations of SHANK3 gene seem to explain the etiology of only a small proportion of cases with autism." (PMID 19566951, 2009). "Our finding suggested that SHANK3 doesn't represent a major susceptibility gene for autism in the autism families ascertained from Chinese Han population." (PMID 19566951, 2009). "In the present study, we investigated the association of SHANK3 polymorphisms and autism in 305 Chinese Han trios." (PMID 19566951, 2009). "We performed an association study between SHANK3 gene polymorphisms and autism in Chinese Han population." (PMID 19566951, 2009). "We analyzed the association between five single nucleotide polymorphisms (SNPs) of the SHANK3 gene and autism in 305 Chinese Han trios, using the family based association test (FBAT)." (PMID 19566951, 2009).
autism (continued). "In this study, we attempted to investigate the association between the SHANK3 gene polymorphisms and autism in 305 Chinese Han trios on a population-based approach using the family-based association test (FBAT)." (PMID 19566951, 2009). "Shank3 and Cntnap2 are autism-associated genes with distinct roles in neurons." (PMID 41062277, 2025). "Our findings in the Shank3-deficient mouse model of autism, together with previous data, suggest that morphological changes in dopaminergic neurons and alterations in neurite growth can influence projection areas, synaptic protein expression, and dopamine receptor levels." (PMID 39654001, 2025). "Similar autism‐like phenotypes have been observed in Shank3‐deficient rodent models." (PMID 40755426, 2025). "Shank3 mutation or deficiency frequently occurs in autism cases." (PMID 38570876, 2024). "Therefore, the present study aimed to evaluate selected components of the GABAergic system in olfactory brain regions and primary olfactory neurons isolated from Shank3-deficient (−/−) mice, which are known for their autism-like behavioral phenotype." (PMID 38183586, 2024). "In addition to common dog diseases, dogs can also suffer from diseases similar to humans, such as tumors like eye tumors and psychiatric disorders like autism, and studies have shown a strong association between SHANK3 and autism in humans." (PMID 39926593, 2024). "Although there is a strong correlation between MAPK and PI3K/Akt signaling pathways and autism, we are more interested in whether MAPKs pathway are involved in regulating Shank3-associated autism." (PMID 38570876, 2024). "However, the role of the hypothalamus in Shank3 deletion or mutation-caused autism is still poorly understood." (PMID 38570876, 2024). "Due to its role as a structural synaptic scaffold for AMPA/NMDA receptors, Shank3 research has principally focused on synaptic dysfunction as the primary driver of pathology in autism in that Shank3 mutations likely interfere with the balance of these receptors." (PMID 37441676, 2023). "Mutations in the gene encoding the synaptic scaffolding protein SHANK3 are detected in 1–2% of patients with autism and intellectual disability, but the mechanisms underpinning the symptoms remain largely unknown." (PMID 37008785, 2023). "For instance, a zebrafish Shank3 mutant model of autism showed that mutations in Shank3 resulted in abnormalities of GI transit and motility due to reductions in serotonin-positive EECs involved in subsequent secretion and peristalsis-associated neural pathways." (PMID 37694110, 2023). "We chose heterozygotes since clinical autism-associated Shank3 mutations are heterozygous." (PMID 37968722, 2023). "The same SHANK3 knockout was also found to increase grooming time and aggressive behaviors, cause learning deficits, and lead to improved pitch discrimination; this latter trait is also commonly found among persons with autism." (PMID 34188957, 2021). "Notably, this was disrupted in a mouse model of autism (Shank3 knockout (KO) mice), even though large numbers of prefrontal neurons are still recruited by socialization in Shank3 KO mice and encode socialization through changes in their activity levels." (PMID 33939689, 2021). "The SHANK3 gene is among the most common and replicated genetic causes of autism." (PMID 32327468, 2020).
autism (continued). "Heterozygous SHANK3 mutations or partial deletions of the long arm of chromosome 22, also known as Phelan–McDermid syndrome, result in a syndromic form of the autism spectrum as well as in global developmental delay, intellectual disability, and several neuropsychiatric comorbidities." (PMID 31788990, 2020). "iPSC-derived cortical neurons isolated from four ASD patients harboring the autism risk gene SHANK3 de novo heterozygous truncating mutations also display significant reduction in SHANK3 mRNA levels and a decrease in dendritic spine density and spine head volumes." (PMID 32460854, 2020). "In addition, SHANK3 modulates the HCN protein levels by direct interaction, and SHANK3 mutations predispose individuals to autism by inducing dysfunction of HCN channels." (PMID 32269286, 2020). "SHANK genes (SHANK1, SHANK2, and SHANK3) encode synaptic folding proteins, and genetic manipulations that alter the expression of these proteins have been used to model the effects of genetic risk factors of autism." (PMID 32383208, 2020). "In addition, loss of one copy of SHANK3 causes Phelan-McDermid or 22q13 deletion syndrome, a syndrome in which Autism occurs in >80% of cases." (PMID 30405356, 2018). "Interestingly, the relevance of most of these mutations for Shank3 function, and their role in autism pathogenesis is unclear." (PMID 30131675, 2018). "This may suggest that social and communicative impairments would be a useful autism endophenotype to be investigated in relation to 22q13.3 deletions and SHANK3 mutations more broadly." (PMID 29126394, 2017). "Interestingly, knockdown of H2A.Z.1, but not H2A.Z.2, led to altered expression of several candidate genes linked to psychiatric disorders such as autism and schizophrenia (Neurexin1, Shank3, CaMK2G, Vamp7, Gsk3b, Tuba8, Grm8, etc.)." (PMID 28856239, 2017). "While mutations in Shank3 may be found in ~0.5% of individuals with autism, this study suggests that epigenetic changes in Shank3 may actually be more widespread." (PMID 27462204, 2016). "The Src homology 3 and multiple ankyrin repeat domains 3 (SHANK3) gene, which encodes for the postsynaptic scaffolding protein SHANK3/ProSAP2, has been identified as one of the few genes which can by itself lead to autism when mutated." (PMID 26137200, 2015). "To understand how variants in SHANK3 would lead to such impairments and manifest in the brain of patients with autism, we assessed the presence of synaptic pathology in Shank3-deficient mice at 5 weeks and 3 months of age, focusing on the stratum radiatum of the CA1 field." (PMID 26137200, 2015). "Upon further analysis, SHANK3 variants were identified in patients ascertained with autism." (PMID 26137200, 2015). "Additionally, prenatal zinc deficiency in animal models influences Shank3, a well described autism-associated gene, at synapses." (PMID 25610379, 2014). "Interestingly, in a mouse genetic model of autism, expression of a single copy of a Shank3 C-terminal deletion mutation results in increased polyubiquitination of both Shank3 and NMDAR GluN1 and a subsequent reduction of GluN1." (PMID 23431475, 2013). "It has been suggested that DIAPH3 might be involved in synaptic activity and function downstream of SHANK3 (chromosome 22q13), a well-documented autism susceptibility gene." (PMID 23840741, 2013). "Higher burdens of rare, potentially deleterious variants were identified in autism cases for three pathway genes previously implicated in syndromic autism spectrum disorder, TSC1, TSC2, and SHANK3, suggesting that genetic variation in these genes also contributes to risk for non-syndromic autism." (PMID 22558107, 2012). "Looking at specific CNV regions, we find evidence to suggest that copy number variation in the SHANK3,region where copy number variation has been previously associated with susceptibility to autism and schizophrenia, is associated with normal variation in fluid intelligence." (PMID 23300510, 2012).
autism (continued). "Indeed several autism-associated genes that can be found at excitatory postsynapses, such as Shank2 and Shank3, MTs and ERK are Zn2+ binding, and Zn2+ regulated proteins." (PMID 23346059, 2012). "In addition, our analysis identified HOMER1, which encodes a postsynaptic density-localized scaffolding protein that interacts with Shank3 to regulate mGluR activity, as a novel autism-risk gene." (PMID 22558107, 2012). "A number of monogenic heritable autism spectrum condition forms have been shown to be caused by loss-of-function mutations in genes that code for synaptic cell adhesion proteins such as the neuroligin and neurexin genes and genes that encode synaptic scaffold proteins such as SHANK3." (PMID 20579107, 2011). "De novo deletions and mutations of SHANK3 have been found in individuals with autism." (PMID 20459802, 2010). "There was few association or linkage study for SHANK3 and autism." (PMID 19566951, 2009). "These might indicate that SHANK3 doesn't represent a major susceptibility gene for autism in the autism families ascertained from Chinese Han population." (PMID 19566951, 2009). "In addition, mutations of the high‐risk autism gene Shank3 in dogs lead to attention deficits." (PMID 39257367, 2024). "Thus, whether AgRP neurons are associated with the Shank3 deficiency-caused autism is still unknown." (PMID 38570876, 2024). "However, it is unclear whether hypothalamus and p38α are involved in the development of autism caused by Shank3 mutations or deficiency." (PMID 38570876, 2024). "The finding that Shank3-deficient mice exhibit altered arborization of GABAergic neurons isolated from the midbrain suggests changes in neurite growth and synaptic connections, potentially affecting signal processing in dopaminergic brain regions under autism-like conditions." (PMID 39334399, 2024). "Overall, it appears that Shank3 deficiency leads to changes in GABAergic synapses in the brain regions that are important for olfactory information processing, which may represent basis for understanding functional impairments in autism." (PMID 38183586, 2024). "However, it is important to note that in other cases where AMPAr hypofunction may be a key pathogenic mechanism, such as in SHANK3-associated autism, AMPAr antagonism may worsen behavioral phenotypes." (PMID 38352654, 2024). "Heterozygous de novo mutations deleting SHANK3 on chromosome 22q13.3 or affecting its coding region are associated with Phelan-McDermid syndrome and observed in 1–2% of patients with both autism and intellectual disability, making this gene a major cause of neurodevelopmental disorder." (PMID 37008785, 2023). "However, increasing evidence is linking SHANK3 gene mutations as a cause of autism." (PMID 33343614, 2020). "It was reported that rare mutations in SHANK3 may contribute to the pathogenesis of autism." (PMID 19566951, 2009). "However, there was few evidence of association between SHANK3 polymorphisms and autism." (PMID 19566951, 2009). "However, the genotype–phenotype correlation reported in both studies suggests that patients with autism with severe language and social impairment might be good candidates for SHANK3 mutation screening." (PMID 18728070, 2009). "Our current data expand on our previous research to understand the involvement of mesolimbic Shank3 expression in autism‐like phenotypes." (PMID 40755426, 2025). "In model organisms, in vivo restoration of protein function using various platforms has shown recovery of AMPAr-mediated dysfunction, perhaps paving the way for future therapies in SHANK3-related autism." (PMID 38352654, 2024).